HDGF (heparin binding growth factor)
Diseases named in the same sentence as HDGF in open-access papers (continued):
Sharing a sentence is not in itself a finding about the gene and the disease.
hepatocellular carcinoma (continued). "For instance, HDGF promotes growth and metastasis of hepatocellular carcinoma cells." (PMID 34895232, 2021). "The HDGF is a 240 amino-acid protein isolated from human hepatoma cells." (PMID 33727914, 2021). "HDGF was identified in order to find a novel growth-stimulating factor for hepatoma cells." (PMID 32545762, 2020). "Additionally, HDGF-reduction in hepatoma cells resulted in the decreased expression of VEGF, and inhibited tumor growth in vivo." (PMID 32545762, 2020). "For instance, METTL3-mediated m6A modification led to LINC00958 upregulation through stabilizing its RNA transcript, and LINC00968 sponged miR-3619-5p to upregulate HDGF expression thereby facilitating the lipogenesis and progression of hepatocellular carcinoma (HCC)." (PMID 32982586, 2020). "The expression of HDGF was detected in several hepatoma-derived cell lines." (PMID 32545762, 2020). "As expected, HDGF showed a growth-stimulating effect on hepatoma cells in vitro." (PMID 32545762, 2020). "We found that nuclear but not cytoplasmic HDGF is closely associated with prognosis of hepatocellular carcinoma (HCC)." (PMID 30004626, 2018). "HDGF is a 26-kDa heparin-binding acidic glycoprotein consisting of 240 amino acids that was originally reported as a secreted protein purified from the conditioned medium of Huh-7 hepatoma cells." (PMID 26101867, 2015). "Moreover, NCL knockdown significantly attenuated the basal and HDGF-stimulated proliferation, invasiveness and anchorage-independent growth of hepatoma cells." (PMID 25938538, 2015). "To further confirm the function of NCL as a cell surface receptor for HDGF, we examined whether neutralization of surface NCL influenced the HDGF uptake of hepatoma cells." (PMID 25938538, 2015). "Moreover, by using fluorescent-labeling HDGF, the cellular uptake assay revealed that prior NCL blockage significantly depleted the fluorescence in HDGF-treated hepatoma cells." (PMID 25938538, 2015). "The endogenous overexpression of HDGF significantly stimulates the proliferation of hepatoma cells." (PMID 26101867, 2015). "HDGF was initially purified from the conditioned medium of a hepatoma cell line." (PMID 26101867, 2015). "HDGF is a prognostic marker in several types of cancer including hepatocellular carcinoma, esophageal squamous cell carcinoma, gastric cancer, intrahepatic cholangiocarcinoma, early-stage cervical adenocarcinoma, gallbladder cancer, and non small cell lung cancer." (PMID 26296979, 2015). "In hepatocellular carcinoma, it was shown that METTL3-mediated N6-methyladenosine modification leads to upregulation of LINC00958, which uptakes miR3619-5p and thus upregulates HDGF expression, which facilitates adipogenesis and advancement of HCC." (PMID 38125749, 2023). "Subsequently, we investigated whether exogenous HDGF enhanced ROS production in hepatoma cells." (PMID 37827291, 2023). "In addition, HDGF significantly increased catalase protein levels in hepatoma cells." (PMID 37827291, 2023). "Likewise, NAC treatment also perturbed the HDGF-induced invasiveness of hepatoma cells." (PMID 37827291, 2023). "Therefore, HDGF promotes ROS generation in hepatoma cells via NCL." (PMID 37827291, 2023). "Moreover, we showed that rHDGF or modulating HDGF by an adenovirus delivery system could accelerate cellular ROS generation, as shown by 2′, 7′ –dichlorofluorescein and MitoSOX Red staining in hepatoma cells." (PMID 37827291, 2023). "Moreover, NCL knockdown significantly abolished the HDGF-induced increase in basal respiration, coupled respiration, maximal oxygen consumption, and spare capacity in hepatoma cells." (PMID 37827291, 2023). "Four publicly available HCC expression datasets were analyzed in order to determine the role of HDGF in hepatocellular carcinoma in vivo." (PMID 35578240, 2022).
hepatocellular carcinoma (continued). "Interestingly, a recent study suggested that HDGF was related to lipogenesis, and the change in the lipid metabolism might partly contribute to the mitosis of the hepatoma cells." (PMID 32545762, 2020). "In addition, HDGF significantly increases the proliferation of hepatoma cells." (PMID 32545762, 2020). "Accordingly, a number of studies have focused on the significance of HDGF as a prognostic marker and have demonstrated its clinical value for oral cancer, esophageal cancer, gastrointestinal stromal tumors, meningiomas, hepatocellular cancer, and non-small cell lung carcinoma." (PMID 31032220, 2019). "Thus, NCL overexpression elicits HDGF upregulation and promotes the malignancy of hepatoma cells." (PMID 25938538, 2015). "In this study, we investigated the HDGF expression in hepatocellular carcinoma (HCC) and its correlation with clinicopathologic features, including the survival of patients with HCC." (PMID 20846397, 2010). "Proteomic analysis of urinary exosomes from 18 hepatocellular carcinoma patients and healthy controls by mass spectrometry revealed increased expression of OLFM4, HDGF, and GDF15 in patients with hepatocellular carcinoma." (PMID 40075875, 2025). "In summary, these findings suggest that activation of HDGF/NCL signaling triggers an increase in intracellular ROS, thereby contributing to hepatoma progression." (PMID 37827291, 2023). "Heparin-binding growth factor (HDGF) was first purified from the Huh-7 cell medium, a human hepatoma-derived cell line." (PMID 34376200, 2021). "Transcription factor hepatoma-derived growth factor (HDGF) is an acidic heparin-binding growth factor, originally isolated from the culture medium of human hepatocellular carcinoma cell line HuH-7." (PMID 34895232, 2021). "In hepatocellular carcinoma (HCC), METTL3-mediated m6A modification enhances the stability of LINC00958 transcript, which can upregulate hepatoma-derived growth factor (HDGF) expression by sponging miR-3619-5p to promote tumor growth." (PMID 33292652, 2020). "HDGF is highly expressed in hepatocellular carcinoma (HCC) cells." (PMID 31162607, 2019). "HDGF has been demonstrated to bind directly to surface nucleolin (NCL) and activate the NCL/PI3K/AKT axis in hepatoma cells during liver carcinogenesis." (PMID 31711427, 2019). "Together, these findings indicate NCL knockdown attenuates the basal and HDGF-stimulated oncogenic behaviours and PI3K/Akt pathway in hepatoma cells." (PMID 25938538, 2015). "It was found LY2940002 application significantly suppressed the HDGF- or NCL-stimulated invasion and colonies formation in hepatoma cells." (PMID 25938538, 2015). "Above all, LY2940002 treatment potently abolished the compounding effect of HDGF supply and NCL overexpression on oncogenic behaviors of hepatoma cells." (PMID 25938538, 2015). "Since the hepatoma-derived cell line Huh-7 autonomously proliferates under serum-free conditions in vitro, we hypothesized the presence of an unknown growth factor in the conditioned medium and succeeded in purifying a new molecule, “hepatoma-derived growth factor (HDGF)”." (PMID 26101867, 2015). "Blockade of surface NCL by antibodies neutralization potently suppressed HDGF uptake and HDGF-stimulated phosphatidylinositol 3-kinase (PI3K)/Akt signaling in hepatoma cells." (PMID 25938538, 2015). "Immunoblot analysis further showed that NCL knockdown potently inhibited the basal and HDGF-stimulated PI3K expression and Akt phosphorylation in hepatoma cells." (PMID 25938538, 2015). "Thus, HDGF may directly induce Akt activation in hepatoma cells through NCL." (PMID 25938538, 2015). "HDGF expression is significantly elevated in tumor tissues compared to adjacent non-tumorous tissues in cancers such as hepatocellular carcinoma and colorectal cancer." (PMID 41278276, 2025).
hepatocellular carcinoma (continued). "In hepatocellular carcinoma, METTL3 mediates the m6A modification of LINC00958, leading to the upregulation of LINC00958 through stabilizing its RNA transcript, then upregulates hepatoma-derived growth factor (HDGF) expression." (PMID 35501316, 2022). "In a previous study, a global analysis that integrated proteome analysis revealed that a lack of hepatoma-derived growth factor (HDGF) genes can limit apoptosis induced by TNF-α." (PMID 33727914, 2021). "Therefore, HDGF promotes the translocation and stability of surface NCL during early exposure and ultimately induces NCL upregulation in hepatoma cells after longer treatment." (PMID 25938538, 2015). "Since PI3K/Akt is the downstream effector of HDGF, we investigated whether NCL overexpression influenced the HDGF/Akt signaling in hepatoma cells." (PMID 25938538, 2015). "It was shown that application of anti-NCL antibodies, but not control IgG, abrogated the HDGF-induced PI3K/Akt phosphorylation in hepatoma cells." (PMID 25938538, 2015). "Thus, unlike TGF-β, HDGF upregulated rather than downregulated the expression of free radical scavenging enzymes in hepatoma cells." (PMID 37827291, 2023). "Since we demonstrated that HDGF induces ROS generation in hepatoma through surface expression of NCL, it seems plausible that HDGF/NCL signaling might modulate the activity of mitochondrial bioenergetics to promote an increase in ROS in hepatoma cells." (PMID 37827291, 2023). "However, the interplay between HDGF and ROS generation has not been elucidated in hepatocellular carcinoma." (PMID 37827291, 2023). "In liver hepatocellular carcinoma (HCC), LINC00958 sponged miR3619-5p up-regulates the liver cancer-derived growth factor (HDGF) expression, which promotes HCC progression and adipogenesis." (PMID 36437914, 2022). "Hepatoma-derived growth factor (HDGF), a secreted protein which was first purified from the culture medium of Huh-7 hepatoma cells, was found to be up-regulated in various cancers like hepatocellular carcinoma, colorectal, pancreatic and non-small cell lung cancers." (PMID 29568375, 2018). "Our results indicate that HDGF does not modulate SVZ precursor cell fates via NCL, the only receptor that has been identified to interact with and mediate the uptake of HDGF in hepatoma cells." (PMID 35293825, 2022).
bladder cancer (34 papers, 2014 to 2026). "For example, in bladder cancer, the m5C modifications of heparin-binding growth factor (HDGF) mRNA are deposited by NSUN2 and are specifically recognized by YBX1 to maintain its stability, thereby driving tumor progression." (PMID 38402198, 2024). "NSUN2 has also been reported to stabilize HDGF mRNA via m5C and to promote the progression of bladder cancer." (PMID 36792587, 2023). "For example, NSUN2‐mediated m5C modification promotes the pathogenesis of bladder cancer by enhancing the binding of YBX1 to HDGF and thereby promotes its expression." (PMID 37228185, 2023). "A previous study has revealed that HDGF silencing inhibited bladder cancer cell tumorigenesis and induced cell apoptosis through the PI3K-AKT signaling pathway." (PMID 36694627, 2023). "Based on the analysis of a bladder cancer cohort in The Cancer Genome Atlas (TCGA) program, HDGF expression is significantly higher in bladder cancer patients compared to healthy tissue." (PMID 37479885, 2023). "For example, YBX1 has been found to be able to work with NSUN2 to stabilize HDGF mRNA to promote the progression of bladder cancer." (PMID 36792587, 2023). "In one report, the m5C modification in the 3’UTR of heparin binding growth factor (HDGF) mRNA can promote the stability of HDGF mRNA, which contributes to bladder cancer progression." (PMID 35603206, 2022). "By binding to m5C methylated sites and recruiting ELAVL1, YBX1 maintains HDGF mRNA stability and therefore exerts an oncogenic role in bladder cancer development through the activation of HDGF." (PMID 32944246, 2020). "The m5C recognition protein YBX1 recognizes m5C-modified mRNA through the W65 indole ring in its cold shock domain and subsequently recruits ELAV like protein 1 (ELAVL1) to stabilize heparin-binding growth factor mRNA, which ultimately promotes bladder cancer cell proliferation and metastasis." (PMID 41326692, 2026). "In addition, HDGF is also overexpressed in our bladder cancer cells, compared to the healthy TRT-HU-1 cells." (PMID 37479885, 2023). "On the other hand, the overexpression of NSUN2 in bladder carcinoma, and thus the m5C aberrant methylation of the oncogenic transcripts of the heparin binding growth factor (HDGF) gene, have been shown to augment mRNA stability and correspond with poor cancer prognosis." (PMID 36768716, 2023). "In addition, NSUN2 promotes the expression of heparin‐binding growth factor (HDGF) and promotes pathogenesis of the bladder cancer." (PMID 37228185, 2023). "That means HDGF functions as an oncogenic gene in the context of bladder cancer." (PMID 35014946, 2022). "In addition, downregulation of HDGF inhibits the tumorigenesis of bladder cancer cells by inactivating the PI3K/AKT signaling pathway." (PMID 34895232, 2021). "In bladder cancer, NSUN2 methylates the 3′ untranslated region (3′-UTR) of the HDGF (hepatoma-derived growth factor) mRNA, installing m5C marks that are bound by YBX1." (PMID 41301491, 2025). "NSUN2 affects the mRNA stability of the heparin-binding growth factor (HDGF) by catalyzing m5C modification in its 3′-untranslated region (3′-UTR), which promotes the pathogenesis of bladder cancer." (PMID 36183976, 2023). "This is consistent with a study in ovarian cancer cells in which extracellular HDGF stimulated the phosphorylation of ERK and promoted tumor development and progression by regulating the PI3K-Akt pathway in bladder cancer cells." (PMID 37301856, 2023). "YBX1 targeted oncogene heparin binding growth factor (HDGF) m5C and stabilize its mRNA to promote pathogenesis of bladder cancer." (PMID 36642732, 2023). "In bladder cancer patients, YBX1 stabilizes oncogenic HDGF (heparin binding growth factor) mRNA by targeting the m5C-modified site on its 3′-UTR." (PMID 37325635, 2023).
bladder cancer (continued). "For example, m5C reader Y-box binding protein 1 can recruit ELAV-like RNA binding protein 1 (ELAVL1) in bladder cancer (BLCA), thus increasing the stability of hepatoma-derived growth factor (HDGF) mRNA and promoting the invasion of BLCA cells." (PMID 37769000, 2023). "YBX1 binds to HDGF mRNA in an m5C-depend manner, and ELAVL1 mediates the half-life of HDGF mRNA by interacting with YBX1, promoting bladder cancer pathogenesis." (PMID 36348434, 2022). "For instance, HDGF down-regulation limits the profile of the PI3K-Akt signaling pathway, dampening bladder cancer cell growth in vitro and in xenograft nude mouse models." (PMID 35014946, 2022). "In bladder cancer, the cytoplasmic protein YBX1 recognizes the NSUN2-dependent m5C site located on the 3'UTR of heparin-binding growth factor (HDGF) mRNA and recruits ELAV-like RNA-binding protein 1 (ELAV1) to improve its stability." (PMID 35562754, 2022). "Among these, the heparin-binding growth factor (HDGF) transcript is methylated by NSUN2 and stabilized by m5C reader YBX1, which in turn facilitates the pathogenesis of bladder cancer." (PMID 34272618, 2021). "In bladder cancer, NSUN2 is involved in pathogenesis promotion through m5C deposition in the 3’ UTR of hepatoma-derived growth factor (HDGF)." (PMID 33922187, 2021). "In bladder cancer, m5C reader YBX1 recognized NSUN2‐induced m5C modification in 3′ UTR of hepatoma‐derived growth factor (HDGF) mRNA and further maintained its stability, therefore driving the oncogenic molecular mechanism of HDGF in bladder cancer." (PMID 38721006, 2024). "It was reported that the m5C regulator YBX1 maintained the mRNA stability of the oncogenic gene heparin binding growth factor (HDGF) by binding to m5C methylated sites and recruiting ELAVL1, thus exerting an oncogenic role in bladder cancer development through the activation of HDGF." (PMID 35252205, 2022). "In bladder cancer, Y-Box Binding Protein 1 (YBX1) has been identified as a an m5C “reader” and was shown to promote carcinogenesis by stabilizing Hepatoma-Derived Growth Factor (HDGF) through an interaction with Elav-Like RNA-Binding Protein 1 (ELAVL1)." (PMID 32708015, 2020). "Similarly, it has also been reported that YBX1 could stabilize its target mRNAs by recognizing the m5C methylation site in the HDGF mRNA and by recruiting ELAV like RNA binding protein 1 (ELAVL1) in bladder cancer." (PMID 35603206, 2022).
lung cancer (24 papers, 2010 to 2025). A malignant neoplasm involving the lung. "HDGF has been implicated in angiogenesis, tumorigenesis, and worse disease prognosis in oral, bladder, and lung cancers." (PMID 39402324, 2024). "EGCG treatment also induced synergistic effect with cisplatin in causing lung cancer cell death and increased cytotoxicity was also noted in HDGF-silenced cells." (PMID 30585192, 2018). "Treatment with EGCG caused three-fold suppression of HDGF and downregulation of HDGF by EGCG was confirmed using anti-HDGF antibodies in lung cancer cell lines." (PMID 30585192, 2018). "PTN is a heparin-binding growth factor that is highly expressed in certain solid cancers, such as in breast and lung cancers." (PMID 40416874, 2025). "Bioinformatics analysis revealed that Midkine (MDK), a heparin-binding growth factor known to promote migration, is highly elevated in breast and lung cancer patients and is related with osteoclast formation." (PMID 40520001, 2025). "Differential expression analysis of epithelial cells showed a significant increase in expression of CXCL1, CXCL2, and HDGF in KRASG12D-driven lung cancer samples compared with non–KRAS-driven lung cancer." (PMID 39782689, 2025). "AFAP1-AS1 can also enhance expression of HDGF through decreasing miR-545-3p levels in lung cancer cells." (PMID 34912717, 2021). "HDGF is related to the regulation of cancer metastasis, and especially to the metastasis of lung cancer." (PMID 28678795, 2017). "Treatment with HDGF antibodies significantly suppresses the proliferation of lung cancer cells, making HDGF a novel therapeutic target for lung cancer." (PMID 26101867, 2015). "Elevated levels of MDK, a heparin-binding growth factor, have been observed in serum collected from patients with a broad range of solid tumors, including lung cancer." (PMID 26279647, 2015). "Several studies have demonstrated that miR-34a retards lung cancer cell growth or induces apoptosis by targeting TGFβR2, Axl, Notch-1, or HDM4, whereas miR-497 does so by targeting HDGF in lung cancer." (PMID 25909221, 2015). "Midkine (MDK) is a heparin-binding growth factor that is highly expressed in many malignant tumors, including lung cancers." (PMID 23976985, 2013). "Antibody targeting HDGF was a novel effective strategy in treating lung cancers." (PMID 36694627, 2023). "Knockdown of AFAP1-AS1 by regulating the miR-545-3p/HDGF axis could promote apoptosis in lung cancer." (PMID 34367998, 2021). "Interestingly, downregulating HDGF with monoclonal antibodies impaired lung cancer growth and vascularity." (PMID 34943783, 2021). "Hepatoma-derived growth factor (HDGF) is considered as a therapeutic target in lung cancer." (PMID 30585192, 2018). "It was concluded that decreasing the levels of HDGF by treatment with EGCG may signify a novel approach in treatment of lung cancer." (PMID 30585192, 2018). "Thus, AFAP1-AS1 silencing could inhibit progression of lung cancer through influencing activity of miR-545-3p/HDGF axis." (PMID 34912717, 2021). "Recently, the significant roles of HDGF in malignant diseases were reported for many non-digestive malignant diseases, including osteosarcoma, endometrial cancer, lung cancer, malignant glioma, cervical cancer, ovarian cancer and breast cancer." (PMID 32545762, 2020). "Likewise, Shih and colleagues found that miR-214 targeted HDGF in HCC, so miR-214 confers drug resistance in lung cancers but could theoretically target HDGF to hinder tumourigenesis." (PMID 34943783, 2021).